LPIN1 (lipin 1)
Diseases named in the same sentence as LPIN1 in open-access papers (continued):
Sharing a sentence is not in itself a finding about the gene and the disease.
rhabdomyolysis (27 papers, 2016 to 2025). Necrosis or disintegration of skeletal muscle often followed by myoglobinuria. "Mutations in the LPIN1 gene are recognized as one of the most common causes of recurrent rhabdomyolysis in the pediatric population." (PMID 39897188, 2025). "While LPIN1 mutations typically cause pediatric-onset rhabdomyolysis, this case highlights the need to consider LPIN1 mutations in adults with episodic myopathy and rhabdomyolysis when other causes are ruled out." (PMID 39897188, 2025). "Mutations R725H (motif II) and G799R (motif IV) in lipin 1 cause rhabdomyolysis, marked by myoglobinuria." (PMID 40680843, 2025). "For comparison, we included the R193H point mutant we previously characterized, and which represents the R725H point mutant found in lipin-1 deficient patients with rhabdomyolysis." (PMID 41109341, 2025). "We reported a rare instance of episodic rhabdomyolysis in an adult patient carrying a heterozygous LPIN1 gene mutation." (PMID 39897188, 2025). "Lipin-1 deficiency (phosphatidic acid phosphatase deficiency) has emerged in the last two decades as a major cause of autosomal recessive fever-induced rhabdomyolysis in young children." (PMID 37239314, 2023). "Life is usually compatible with most metabolic myopathies, with notable exceptions, such as early-onset FAO defects; lipin-1 deficiency; and life-threatening metabolic crises, including lactic acidosis, severe hypoglycemia, and rhabdomyolysis." (PMID 37239314, 2023). "One important question is why do patients with LPIN1 mutations, which impact the metabolism of de novo synthesis of glyceropholipids, develop rhabdomyolysis with illness?" (PMID 35242575, 2022). "Previously, a cohort of individuals with non-Lpin1 caused rhabdomyolysis was described with a shortened time to CK levels resolution with steroid administration." (PMID 35242575, 2022). "LPIN1 plays a role in lipid synthesis and storage, and mutation in LPIN1 is associated with myoglobinuria as well as rhabdomyolysis." (PMID 35207686, 2022). "Mutations of LPIN1 in humans have been identified as a major cause of recurrent, early-onset myoglobinuria and rhabdomyolysis (MIM#268200)." (PMID 33456573, 2021). "There were also patients with chronic pulmonary disease in the intensive care unit, acute lymphoblastic leukemia, lipin-1 deficiency (rhabdomyolysis + acute renal failure with hemodialysis), and CHAPLE syndrome (CD55 deficiency)." (PMID 34431642, 2021). "More than 90% recessive LPIN1 mutations, including homozygous or compound heterozygous genotypes, cause myoglobinuria and rhabdomyolysis of which more than 80% of patients developed in early childhood (<5 years old)." (PMID 33456573, 2021). "Hitherto, 46 homozygous or compound heterozygous mutations in LPIN1 gene from 48 cases have been identified in humans 14, 15, 35-46; among which 83.3% cause myoglobinuria, and 100% lead to rhabdomyolysis symptoms, mostly in childhood." (PMID 33456573, 2021). "In the future, more active genetic test strategy and detailed prophylactic care education should be taken in patients with severe recurrent rhabdomyolysis, who are the high risk group of LPIN1 genetic defects." (PMID 32410653, 2020). "Autosomal recessive mutations in LPIN1 were recognized as one of the most common causes of pediatric recurrent rhabdomyolysis in western countries." (PMID 32410653, 2020). "Here we report a Chinese pediatric case of recurrent rhabdomyolysis with compound heterozygous variants (p.Arg388* and p.Arg810Cys) in the LPIN1 gene." (PMID 32410653, 2020). "This study aims to report the first pediatric case of recurrent rhabdomyolysis with a novel LPIN1 mutation in China mainland in order to raise the awareness of both pediatricians and patients." (PMID 32410653, 2020). "Lpin1 is required for adipocyte differentiation and Lpin1 deficiency has been shown to cause severe rhabdomyolysis in children." (PMID 30089464, 2018).
rhabdomyolysis (continued). "The treatment of rhabdomyolysis in LPIN1 deficiency is symptomatic: aggressive intravenous fluid administration and monitoring of electrolytes, kidney, and cardiac functions as for episodes of rhabdomyolysis of any cause." (PMID 30477112, 2018). "Autosomal recessive LPIN1 deficiency is one of the most common causes of severe recurrent rhabdomyolysis in childhood." (PMID 30477112, 2018). "Instead, we and others showed that deleterious LPIN1 mutations cause recurrent severe pediatric clinical episodes of rhabdomyolysis, a syndrome resulting from the massive breakdown of skeletal muscle fibers, leading to myoglobinuria." (PMID 28986436, 2017). "In this study, we performed a systematic histopathological, biochemical, and gene expression analysis of adipose tissue biopsies from human patients harboring LPIN1 biallelic inactivating mutations and affected by recurrent episodes of severe rhabdomyolysis." (PMID 28986436, 2017). "This includes D804N and D804H in lipin-1, which results in loss-of-function and rhabdomyolysis." (PMID 41109341, 2025). "Typically, patients with homozygous or compound heterozygous LPIN1 mutations experience episodes of severe rhabdomyolysis (creatine kinase (CK) levels exceeding 10,000 U/L), often precipitated by triggers such as febrile illness, intense physical exercise, or fasting." (PMID 39897188, 2025). "Interestingly, the analogous mutation in lipin-1 R725H also results in loss-of-function, causing rhabdomyolysis." (PMID 41109341, 2025). "Historically, LPIN1 mutation induced rhabdomyolysis was hypothesized to be caused by a combination of genetic susceptibility and an environmental risk." (PMID 35242575, 2022). "However, the patient with LPIN1 deficiency also had an episode of rhabdomyolysis requiring intensive care admission." (PMID 33456573, 2021). "Mutations in the lipin 1 gene (LPIN1) are a major cause of severe rhabdomyolysis in early childhood, and the heterozygous carrier state may predispose one to statin-induced myopathy." (PMID 32028610, 2020). "Mutations in LPIN1 were gradually recognized as the one of the most common causes of recurrent rhabdomyolysis, as the incidence reported for patients suffering from severe rhabdomyolysis with onset before age 6 years and creatine kinase (CK) > 10,000 U/L reaches 46% by a series of studies." (PMID 32410653, 2020). "Moreover, deleterious LPIN1 mutations cause paediatric rhabdomyolysis while fat distribution, average weight and plasma biochemical variables are normal." (PMID 27344312, 2016). "Moreover, in humans, mutation of LPIN1 causes severe rhabdomyolysis." (PMID 36428957, 2022). "LPIN1 deficiency is diagnosed through clinical evaluation, detailed history, laboratory studies evaluating CK and urine myoglobin levels, muscle biopsy (no longer recommended), and genetic testing to distinguish inherited from acquired causes of rhabdomyolysis." (PMID 35242575, 2022). "Here, we present a rare case of adult-onset myopathy and rhabdomyolysis in a 48-year-old male firefighter, a heterozygous carrier of an LPIN1 exon 18 deletion." (PMID 39897188, 2025). "This case involves an adult man experiencing recurrent, moderate rhabdomyolysis due to a heterozygous LPIN1 exon deletion, with an otherwise unremarkable workup." (PMID 39897188, 2025). "LPIN1-related rhabdomyolysis is still quite new to physicians due to its seemly low-incidence especially in Asian countries." (PMID 32410653, 2020). "Rare variants in several metabolic myopathy genes including CACNA1S, CPT2, LPIN1, PYGM and RYR1 increase myopathy/rhabdomyolysis risk following statin exposure." (PMID 31861911, 2019). "Lipin 1 gene (LPIN1) mutations lead to cellular energy deficiency and cause up to 50% of the rhabdomyolysis episodes seen in pediatric patients." (PMID 30477112, 2018). "Currently, there is no definitive cure for episodic rhabdomyolysis linked to LPIN1 mutations, characterized by subjective fatigue, muscle weakness, and stiffness." (PMID 39897188, 2025).
rhabdomyolysis (continued). "LPIN1 deficiency is an autosomal recessive disease.The pathophysiological basis of LPIN1 deficiency, including the associated rhabdomyolysis, has not be fully elucidated." (PMID 35242575, 2022). "Several studies have shown that Lipin 1 deficiency is linked to recurrent rhabdomyolysis in human children, suggesting that Lipin 1 PAP activity is involved in the acute syndromes of rhabdomyolysis." (PMID 34576941, 2021). "Inflammatory inducers are usually produced when the body is under catabolic stress and the resulting suppressed lipin 1 activity may lead to rhabdomyolysis." (PMID 31723421, 2019). "In contrast, deleterious mutations in the LPIN1 gene in humans, which lead to recurrent rhabdomyolysis in childhood, do not compromise adipose tissue." (PMID 27344312, 2016). "However, mutations in the human gene encoding lipin 1 (LPIN1) do not result in a similar phenotype but have been linked to the development of recurrent, early-onset, pediatric rhabdomyolysis and myoglobinuria (OMIM #268200)." (PMID 33986192, 2021).
Hepatic steatosis (23 papers, 2011 to 2025). Steatosis is a term used to denote lipid accumulation within hepatocytes. "Lpin1, which encodes lipin 1, was first identified as the gene deleted in fatty liver dystrophic (fld) mice, which exhibit severe lipodystrophy associated with systemic metabolic abnormalities." (PMID 39405118, 2024). "There was a significant increase of genes associated with hepatic steatosis (Cidea, Cidec, and Plin4) and fibrosis (Col1a1) in Adn-Lpin1–/– livers on both diets compared with their diet-matched control mice." (PMID 39405118, 2024). "Fatty liver dystrophy (fld) mice that harbored a spontaneous Lpin1 mutation exhibited life-long lipodystrophy and genetically programmed early postnatal fatty liver and hyperlipidemia." (PMID 37964368, 2023). "Hepatic steatosis was caused by the LPIN1-induced suppression of long-chain acyl-CoA synthetases (ACSLs) expression." (PMID 36552725, 2022). "PAP is a rate-limiting enzyme for hepatic triglyceride synthesis, and the activity and expression of the lipin-1 gene encoding PAP were increased in HFD-fed obese mice or ob/ob mice, while deficiency of lipin-1 attenuated hepatic steatosis." (PMID 27213439, 2016). "Previous research depicted DHA as able to alleviate alcoholic fatty liver by regulating lipin 1 signaling via the inhibition of the ER stress-JNK/CHOP-mitochondrial cascade." (PMID 37964368, 2023). "During hepatic steatosis, the interplay of the circRNA, miRNA, and LPIN1 exposes several unexpected yet crucial pathways." (PMID 36552725, 2022). "Protein–protein interaction analysis indicated that lycopene improved hepatic steatosis by regulating the TG metabolic process and lipid metabolic process, mainly regulating the expression of LPIN1." (PMID 34796193, 2021). "Of significance, both Rgs16 and Lpin1 were identified by IPA® analysis as part of a subset of molecules affecting liver steatosis in the SHS-exposed mice." (PMID 32075112, 2020). "Inhibition of mTORC1 in the liver significantly impairs SREBP function and makes mice resistant, in a lipin 1-dependent fashion, to the hepatic steatosis and hypercholesterolemia induced by a high fat and cholesterol diet." (PMID 32770935, 2020). "Acute knockdown of lipin proteins circumvents some of these compensatory effects and has revealed pathophysiological roles for lipin 1 and 2 in mouse models of fatty liver disease." (PMID 33003344, 2020). "The circRNA_021412/miR-1972/LPIN1 (lipin 1) axis participated in the regulation of hepatic steatosis." (PMID 30836719, 2019). "Based on circRNA-miRNA-mRNA network analysis, decreased circRNA_021412 levels, and miR-1972 inhibition of LPIN1, the circRNA_021412/miR-1972/LPIN1 signaling cascade appears to be partially involved in regulating hepatic steatosis." (PMID 30931332, 2019). "The bridging of GO and pathway qualified LPIN1 a critical part in circRNAs' regulation of hepatic steatosis." (PMID 28717649, 2017). "Because of these reasons, abnormality in circRNA_021412/miR-1972/LPIN1 signaling cascade contributes to the hepatic steatosis via disrupting the balance of lipogenesis and catalytic separation." (PMID 28717649, 2017). "Tang’s study revealed that Lusisnthriding, derived from dendrobium, can stimulate the activation of FXR, thereby mitigating hepatic steatosis in mice on a high-fat diet by suppressing the expression of fatty acid synthesis genes, such as Srebp1c, Fas, Scd-1, Dgat1, and Lpin1." (PMID 39769418, 2024). "Regarding LPIN1 rs13412852 SNP distribution, the risk allele C was more frequently observed in the patients with hepatic steatosis irrespective of the history of diabetes." (PMID 34746177, 2021).
Hepatic steatosis (continued). "The decrease in SIRT3 levels might activate an adaptive mechanism through the increase in nuclear HIF-1α and LIPIN 1 levels to attenuate hepatic steatosis." (PMID 32912335, 2020). "Interestingly, deletion of lipin 1 in myeloid cells markedly attenuated hepatic inflammation while concomitantly exacerbating hepatic steatosis in another model of AFLD." (PMID 33003344, 2020). "Interestingly, interaction of these circRNA, miRNA, and LPIN1 reveals some novel, yet important, mechanisms during hepatic steatosis." (PMID 28717649, 2017). "However, when hepatic steatosis was examined in liver-specific lipin 1 knockout mice fed a diet containing high amounts of ethanol, alcoholic hepatic steatosis and liver diseases were exacerbated by lipin 1 deficiency." (PMID 26273583, 2015). "LPIN1 also serves as the coactivator of transcription factors (PPARα, PGC-1α), both of which take the central place during hepatic steatosis." (PMID 28717649, 2017).
lipodystrophy (23 papers, 2006 to 2024). A congenital or acquired disorder characterized by abnormal loss or redistribution of the adipose tissue in the body. "Evidence has emerged that lipin-1 deficiency leads to cardiac dysfunction in mice due to lipodystrophy, modified hormonal regulation, and fuel availability." (PMID 34722683, 2021). "A null mutation in the lipin-1 gene leads to lipodystrophy in mice, and is characterized by (i) loss of adipose tissue, (ii) deficiency in adipocyte differentiation, and (iii) eventually to insulin resistance and circulating hyperlipidemia." (PMID 31133852, 2019). "The rat model with a dominant negative mutation in the Lpin1 gene (the Lpin11Hubr rats) presents a milder but analogous form of lipodystrophy, characterized by impaired expression of key transcriptional adipogenic factors such as PGC1α and PPARα." (PMID 28986436, 2017). "Previous studies have established that lipin-1 plays a major role in fat metabolism in rodents, with lipin-1 deficiency causing lipodystrophy features in mice and rats." (PMID 27344312, 2016). "Indications for this are supported by additional rare variants we found in AGPAT2 and LPIN1 lipodystrophy genes." (PMID 26176221, 2015). "Mice carrying inactivating mutations of the Lpin1 gene are characterized by manifested lipodystrophy features, with a severe reduction of total fat mass, presence of abnormal adipocytes with multilocular LDs, and a significant increase of immature adipocytes in the adipose tissue." (PMID 28986436, 2017). "How AGPAT2 and LPIN1 mutations cause lipodystrophy is uncertain." (PMID 23740690, 2013). "Indeed, Lpin1 loss-of-function induces steatosis and juvenile lethality in the "fatty liver dystrophy" (fld) mice, a model of human lipodystrophy." (PMID 17612398, 2007). "LPIN1 encodes lipin, a protein important for adipocyte differentiation and function that plays a role in glucose and lipid homeostasis and has been associated with human lipodystrophy." (PMID 16859563, 2006). "In mice, adipocyte restricted deletion of Lipin-1 strongly affects adipocyte TG synthesis, leads to PA accumulation, and induces lipodystrophy." (PMID 35250856, 2022). "The observations that the gene encoding for lipin-1 is prevalently expressed in adipose tissue in human beings and mouse make LPIN1 a top-rank candidate for human lipodystrophy." (PMID 28986436, 2017). "We used human fat biopsies from patients carrying inactivating mutations in the LPIN1 gene in both alleles to explore whether impairment of lipin-1 is associated with metabolic, developmental, or histopathological defects that can be ascribed to lipodystrophy or adipose tissue deficiencies." (PMID 28986436, 2017). "LPIN1 is reported to be a candidate gene for human lipodystrophy syndromes as common SNPs in LPIN1 of lipodystrophy patients have been identified." (PMID 21655371, 2008). "In contrast to Lipin 1 deficiency in mice, human Lipin 1 mutations cause muscle pain and weakness without lipodystrophy." (PMID 32475074, 2020). "A case control study showed that in subcutaneous adipose tissue from HIV-infected patients on cART presenting lipodystrophy (LS), the levels of miRNA-218 were upregulated and those of lipin-1, a putative target gene of miRNA-218, were downregulated compared with HIV-negative subjects." (PMID 31133852, 2019). "While mutations in the murine Lpin1 gene cause lipodystrophy and its knockdown in mouse 3T3-L1 cells impairs adipogenesis, deleterious mutations of human LPIN1 do not affect adipose tissue distribution." (PMID 27344312, 2016). "The role of lipins in human adipogenesis is still undefined: mutations in the LPIN1 gene have not yet been detected in human lipodystrophy." (PMID 27344312, 2016). "In contrast to AGPAT2, LPIN1 mutations have been found to be associated with lipodystrophy only in mouse models; there are no known human LPIN1 mutations causing lipodystrophy." (PMID 23740690, 2013).